DIRAS3 (DIRAS family GTPase 3)
Diseases named in the same sentence as DIRAS3 in open-access papers (continued):
Sharing a sentence is not in itself a finding about the gene and the disease.
breast carcinoma (26 papers, 2007 to 2025). "DIRAS3, one important gene in our risk score model, is an imprinted tumor suppressor gene that also plays a very vital role in ovarian and breast cancer." (PMID 34447636, 2021). "DIRAS3 expression has been shown to be associated with chemosensitization to paclitaxel via cell cycle arrest at the G2/M stage in breast cancer cells." (PMID 33042843, 2020). "Another interesting observation regarding the DIRAS3 gene in carcinogenesis comes from breast cancer studies, where downregulation of its expression correlated with brain metastases." (PMID 38203733, 2024). "Under the synergetic influence of dLAN and melatonin, the activated STAT3 inhibits DIRAS3 in an epigenetic manner, resulting in decreased autophagic activity and increased resistance of breast cancer to paclitaxel." (PMID 37190065, 2023). "Chemotherapy of breast cancer initiates ectopic expression of DIRAS3/ARHI, inducing autophagy and initiating tumor dormancy." (PMID 36831154, 2023). "Examination of dormant breast cancer cells revealed that the expression of the tumor suppressor gene DIRAS3/ARHI (which suppresses the AKT-mTOR pathway and activates autophagy) was high." (PMID 36831154, 2023). "The expression of DIRAS3, GPR171 and RAC2, genes associated with brain metastasis, was reduced in metastatic breast cancer, and GPR171 was found to promote brain metastasis of breast cancer cells by inducing B cells and thereby." (PMID 36212434, 2022). "In conclusion, the expressions of DIRAS3, GPR171, and RAC2 genes associated with brain metastasis were reduced in metastatic breast cancer and were strongly associated with overall breast cancer survival." (PMID 36212434, 2022). "The re-expression of DIRAS3 was reported to induce autophagic cell death in ovarian and breast cancer cells." (PMID 33038921, 2020). "For example, in ovarian and breast cancers DIRAS3 has been found to inhibit cell migration, induce autophagy and increase sensitivity to chemotherapy." (PMID 30043279, 2018). "The PI3K/AKT/mTOR pathways can be inhibited by Diras Family GTPase 3 (DIRAS3), which is found to be enriched in dormant breast cancer cells, suggesting that autophagy may contribute to tumor dormancy in breast cancer and thus plays a role in chemoresistance." (PMID 37190065, 2023). "Furthermore, in ovarian and breast cancers, DIRAS3 inhibits cell migration, induces autophagy, and increases sensitivity to chemotherapy." (PMID 36212434, 2022). "In addition, DIRAS3 is capable of suppressing cell migration and inducing autophagy in ovarian and breast cancers." (PMID 35170376, 2022). "Indeed, PITX2 regulates DIRAS3 in lung cancer, and the re-expression of DIRAS3 promotes autophagy in breast cancer, thus enhancing the inhibitory effect of paclitaxel on breast tumor cells." (PMID 34663249, 2021). "It has been demonstrated previously that the transcription of DIRAS3 and GNG12-AS1 is coordinately downregulated in breast cancers." (PMID 38277283, 2024). "Only GPR171, DIRAS3, and RAC2 were strongly correlated with the overall survival of breast cancer patients." (PMID 36212434, 2022). "The analysis showed that only GBP2, GPR171, DIRAS3, and RAC2 were significantly down-regulated in expression in metastatic breast cancer compared with primary breast cancer tumors." (PMID 36212434, 2022). "Expression difference analysis showed that GBP2, GPR171, DIRAS3, and RAC2 were significantly down-regulated in expression in metastatic breast cancer compared with primary breast cancer tumors." (PMID 36212434, 2022). "We performed expression analyses of five genes (GBP2, GPR171, DIRAS3, RAC2, CACNA1D) obtained from the LASSO model to observe their expressions in primary breast cancer and metastatic breast cancer." (PMID 36212434, 2022). "To further explore the biological pathways most relevant to the pathogenesis of breast cancer brain metastasis, we performed GSEA analysis on GPR171, DIRAS3, and RAC2." (PMID 36212434, 2022).
breast carcinoma (continued). "Moreover, the expression levels of DIRAS3, GPR171, and RAC2 were strongly correlated with the overall survival of breast cancer patients." (PMID 36212434, 2022). "The analysis showed that GBP2 was not significantly different from the overall survival of breast cancer patients, while GPR171, DIRAS3, and RAC2 were strongly associated with the overall survival of breast cancer patients." (PMID 36212434, 2022). "Notably, in the present study, our results also showed that DIRAS3, GPR171, and RAC2 were less expressed in tumors that developed metastatic disease compared with primary breast cancer tumors." (PMID 36212434, 2022). "DIRAS3, previously known as ARHI, is a small GTPase, initially reported as an antitumoral protein since its expression is downregulated in certain cancers, such as ovarian, pancreatic, lung, and breast cancers." (PMID 34680951, 2021). "DIRAS3 overexpression can induce cell cycle arrest in G0/G1 and promote cell cycle arrest in G2/M induced by the HDAC (histone deacetylase) inhibitor TAS in ovarian and breast cancers." (PMID 30043279, 2018). "Unlike the Ras and Rap oncogenes, DIRAS3 re-expression enhances apoptosis and autophagic cell death in ovarian and breast cancer cells, indicating that it could function as a tumor suppressor." (PMID 33038921, 2020). "Moreover, as observed in breast cancer cell lines, GNG12-AS1 has the potential to reduce cell migration after its knockdown, but independent of DIRAS3." (PMID 38277283, 2024).
glioma (8 papers, 2011 to 2025). A benign or malignant brain and spinal cord tumor that arises from glial cells (astrocytes, oligodendrocytes, ependymal cells). "This study expands upon our previous findings about the roles of BST2 and DIRAS3 in the evasion of the glioma immune milieu by examining their direct regulatory effects on tumor cell invasion and migratory capabilities." (PMID 40649981, 2025). "Integrating prior research with our current findings, we establish BST2 and DIRAS3 as key regulatory genes governing T-cell-mediated immune evasion in glioma." (PMID 40649981, 2025). "Given their evolutionarily conserved immunoregulatory functions across solid tumors, BST2 and DIRAS3 emerge as novel biomarkers for glioma immunotherapy." (PMID 40649981, 2025). "Studies on the regulation and function of DIRAS-3 have been published on various types of cancers including glioma." (PMID 34680261, 2021). "Functional validation experiments demonstrated that the knockdown of BST2 or DIRAS3 expression in glioma cells significantly suppresses their in vitro migration and invasion capabilities, confirming their critical regulatory roles in malignant phenotypic progression." (PMID 40649981, 2025). "Future research should focus on validating these hypotheses and exploring the therapeutic potential of targeting BST2 and DIRAS3 in glioma treatment." (PMID 40649981, 2025). "DIRAS3 (also known as ARHI) is a known tumor suppressor gene and overexpression of DIRAS3 resulted in suppression of glioma cell proliferation, arrest of cell-cycle progression, reduction in cell migration and invasion, and promotion of cell apoptosis." (PMID 28500050, 2017).
prostate carcinoma (6 papers, 2007 to 2022). A carcinoma that arises from epithelial cells of the prostate gland. "DIRAS3 is an oncogene involved in tumor development and autophagy, and low expression of DIRAS3 is associated with high malignancy in ovarian, breast, and prostate cancers." (PMID 36212434, 2022). "Low expression of DIRAS3 is associated with high malignancy of ovarian, breast, and prostatic cancers, while high expression predicts good prognosis of ovarian and pancreatic cancers." (PMID 30043279, 2018). "Overall, the upregulation of MIR222 could not only inhibit the expression of tumor suppressors such as target genes DIRAS3 and DCTN6 in prostate cancer but also prove that obesity has a strong correlation with cancer metastasis." (PMID 35164166, 2022).
glioblastoma (5 papers, 2009 to 2025). The most malignant astrocytic tumor (WHO grade IV). "The migratory and invasive potential of BST2/DIRAS3 in glioblastoma has only been validated in vitro by our current studies; pertinent marker assays that target the tumor microenvironment are required." (PMID 40649981, 2025). "A study found that Diras3 inhibits proliferation and activation of NF-κB in glioblastoma.Therefore, this gene may become a target of DR treatment and diagnosis." (PMID 29785346, 2018). "Since there were reports on the role of DIRAS-3, another family member of small Ras-GTPases, in resistance to chemotherapeutic agents, we were interested to evaluate whether DIRAS-1 or -2 could mediate chemoresistance in glioblastoma cells." (PMID 34680261, 2021). "DIRAS3 (DIRAS family GTPase 3), namely ARHI, is an imprinted anti‐oncogene and a negative prognostic biomarker in glioblastoma multiforme." (PMID 35611939, 2022).
gastric cancer (4 papers, 2018 to 2022). A primary or metastatic malignant neoplasm involving the stomach. "The IHC showed down-regulation of p-AKT and up-regulation of α-catenin in DIRAS3-BGC-823 xenograft, possibly indicating that DIRAS3 expression inhibited the malignant behavior of gastric cancer cells by the p-AKT and α-catenin pathways." (PMID 30043279, 2018). "To identify the clinical significance of level of DIRAS3 and the level of autophagy, we examined the associations between DIRAS3, p62 and LC3B-II levels with the clinicopathological characteristics of gastric cancer." (PMID 30043279, 2018). "Moreover, the preceding study also stated that DIRAS3 over-expression also suppressed extracellular matrix degradation, and further diminished cell migration and invasion in gastric cancer." (PMID 35170376, 2022). "We then choose BGC-823 cells to ascertain whether the aggressiveness of these gastric cancer cells would be suppressed by DIRAS3 overexpression." (PMID 30043279, 2018). "Based on these results, we speculated that DIRAS3 overexpression inhibits the malignant behavior of gastric cancer cells possibly by reducing the activity of the p-AKT/mTOR pathway." (PMID 30043279, 2018). "The promotion of autophagy by DIRAS3 in gastric cancer (GC) cells was explored, which might explain its inhibitory role in gastric cancer cells." (PMID 30043279, 2018). "Using immunohistochemistry, we determined the levels of DIRAS3, p62 and LC3B-II in gastric cancer and adjacent normal gastric mucosa." (PMID 30043279, 2018). "So, we used LC3B-II and p62 levels as markers to detect autophagy and investigated the levels of DIRAS3, p62 and LC3B-II (indicated by punctate staining), and their clinical significance in 420 gastric cancer specimens." (PMID 30043279, 2018). "In our study, to test whether DIRAS3-induced gastric cancer cell migration depends upon autophagy, we chose to establish a stable knockdown of ATG5 in BGC-823 gastric cancer cells." (PMID 30043279, 2018). "First, methyl thiazolyltetrazolium (MTT) assay and clonogenic assay showed DIRAS3 overexpression led to reduced proliferation rates and colony formation rate in BGC-823 cells, suggesting that DIRAS3 suppressed clonogenicity of gastric cancer cells and thus inhibited proliferation." (PMID 30043279, 2018). "Furthermore, to test whether DIRAS3-induced gastric cancer cell migration depends upon autophagy, we successfully knocked down autophagy-initiating factor ATG5 together with DIRAS3 overexpression in BGC-823 cells." (PMID 30043279, 2018).
glaucoma (4 papers, 2011 to 2024). Increased pressure in the eyeball due to obstruction of the outflow of aqueous humor. "In humans, Diras3 and Tmtc2 are implicated in the onset of glaucoma, a progressive optic neuropathy caused by the loss of RGCs, further confirming the important role of Oc proteins and their target genes in the onset of human diseases." (PMID 39768162, 2024). "Of those genes, DIRAS3 (FC = 1.935) is the only gene with any association with glaucoma or IOP regulation." (PMID 34440692, 2021). "In humans, Diras3 is involved in functions and pathways relevant to glaucoma." (PMID 33816460, 2021).
lung carcinoma (3 papers, 2008 to 2022). "Moreover, it would be prudent to further explore the relationship between DIRAS3 expression and its migration and invasion abilities in different types of lung cancer cells to fully utilize the diagnostic and therapeutic roles of DIRAS3 in NSCLC." (PMID 35170376, 2022). "Subsequently, we examined the effect of DIRAS3 over-expression or knockdown in different lung cancer cells on their malignant phenotypes, with the help of transwell cell migration and invasion assays, and Western blot analyses." (PMID 35170376, 2022). "Supportedly, the upregulated DIRAS3 has been demonstrated to restrict lung cancer cell proliferation and invasion while inducing apoptosis." (PMID 35170376, 2022).
pancreatic cancer (3 papers, 2018 to 2023). "For instance, in the context of ovarian, lung and pancreatic cancer, the tumor suppressor DIRAS3 binds to the α5 helix region of KRAS in the same pocket as P14B." (PMID 36614192, 2023).
thyroid cancer (3 papers, 2013 to 2024). "Cancer-protective action of both RASSF1A and DIRAS3 are affected in thyroid cancer as a result of gene expression silencing, mainly hypermethylation in the promoter region and loss of heterozygosity, respectively." (PMID 38203733, 2024). "Some studies have shown that the decrease in DIRAS3 expression is more prominent in younger patients with thyroid cancer, indicating the potential role of DIRAS3 in the aggressive behaviour of thyroid tumours in certain age groups." (PMID 38203733, 2024). "In Zhu and Qu’s study, the immune-expression levels of DIRAS3 (ARHI) and Beclin1 proteins in thyroid cancer tissues were significantly lower than in adjacent tissues." (PMID 38203733, 2024).
follicular thyroid cancer (2 papers, 2019 to 2024). "Particularly, DIRAS3 (*605193) is a maternally imprinted tumor suppressor gene, located in 1p31 and implicated in growth and ovarian, breast and follicular thyroid cancer." (PMID 30916492, 2019).
lung adenocarcinoma (2 papers, 2022). A carcinoma that arises from the lung and is characterized by the presence of malignant glandular epithelial cells. "Next, in order to further investigate the role of DIRAS3 in the migration and invasion of NSCLC cells, we silenced or over-expressed DIRAS3 in human lung adenocarcinoma cell lines (HCC827 and A549), respectively." (PMID 35170376, 2022).
lymph node metastasis (2 papers, 2018 to 2022). "The level of DIRAS3 protein was associated with Lauren’s type, lymph node metastasis, distant metastasis, and TNM stage, but not with age, gender, Borrmann’s type, WHO’s histological type, and depth of invasion." (PMID 30043279, 2018).
ovarian tumors (2 papers, 2016 to 2019). "The tumor suppressor ARHI (DIRAS3) is a potent inducer of autophagy and non-apoptotic cell death in vitro and is down-regulated or lost in over 60 % of primary ovarian tumors." (PMID 27784287, 2016).
autoimmune thyroid disease (1 paper, 2022). Inflammatory disease of the thyroid gland due to autoimmune responses leading to lymphocytic infiltration of the gland. "In addition, GSEA analysis showed that DIRAS3, GPR171, and RAC2 are involved in signaling pathways such as ECM–receptor interaction, complement and cohesion cascades, adhesion plaques, allograft rejection, autoimmune thyroid disease, graft-versus-host disease, and cell adhesion molecules." (PMID 36212434, 2022).
cardiomyopathy (1 paper, 2020). A disease of the heart muscle or myocardium proper. "In cardiomyopathy rat models, lncRNA H19 silenced DIRAS3 expression, promoted MTOR phosphorylation and inhibited autophagy in cardiomyocytes." (PMID 32301281, 2020).
diabetic cardiomyopathy (1 paper, 2017). Diabetic cardiomyopathy is a disorder of the heart muscle in people with diabetes. "In conclusion, our study suggested that H19 could inhibit autophagy in cardiomyocytes by epigenetically silencing of DIRAS3, which might provide novel insights into understanding the molecular mechanisms of diabetic cardiomyopathy." (PMID 27903964, 2017).
head and neck squamous cell carcinoma (1 paper, 2020). A squamous cell carcinoma that arises from any of the following anatomic sites: lip and oral cavity, nasal cavity, paranasal sinuses, pharynx, larynx, and salivary glands.
hepatocellular carcinoma (1 paper, 2022). A malignant tumor that arises from hepatocytes. "The GTP-binding protein Di-RAS3 (DIRAS3), a member of the Ras superfamily, is known to be poorly expressed in a plethora of malignancies, including ovarian, breast, and hepatocellular carcinomas." (PMID 35170376, 2022).
infertile (1 paper, 2018). "In total, we identified the aberrant methylation of H19, GNAS, and DIRAS3 in 19.3%, 21.5%, and 22.2% of the 135 infertile males, respectively." (PMID 30373665, 2018).
lentivirus infection (1 paper, 2022). Virus diseases caused by the Lentivirus genus. "Two weeks after the lentivirus infection, DIRAS3 protein levels in the cell lines were detected with the help of a Western blot assay." (PMID 35170376, 2022).
lung squamous cell carcinoma (1 paper, 2022). "Similarly, we silenced or over-expressed DIRAS3 in human lung squamous cell carcinoma cell lines (H520 and H2170), and came across similar results." (PMID 35170376, 2022).
malnutrition (1 paper, 2021). Inadequate nutrition resulting from poor diet, malabsorption, or abnormal nutrient distribution. "Additionally, the expression of DIRAS3 is up-regulated under conditions of malnutrition, which leads to the induction of autophagy." (PMID 33881140, 2021).
non-small cell lung carcinoma (1 paper, 2022). A group of at least three distinct histological types of lung cancer, including non-small cell squamous cell carcinoma, adenocarcinoma, and large cell carcinoma. "Growing evidence has correlated the DIRAS3 gene with tumor progression, but its role in non-small cell lung cancer (NSCLC) is rarely reported." (PMID 35170376, 2022).
osteosarcoma (1 paper, 2018). A usually aggressive malignant bone-forming mesenchymal neoplasm, predominantly affecting adolescents and young adults. "Suppressing methylation of DIRAS3 by Zebularine can elevate DIRAS3 expression and enhances apoptosis in osteosarcoma cells." (PMID 30043279, 2018).
thyroid (1 paper, 2024). "The decreased expression of tumour suppressors RASSF1A and DIRAS3 genes—broadly observed in cancerous tissues compared to normal thyroid tissues—proved its involvement in thyroid carcinogenesis." (PMID 38203733, 2024).
thyroid tumours (1 paper, 2024). "Expression of DIRAS3 has been found to be dysregulated in various types of cancers, including thyroid neoplasms." (PMID 38203733, 2024).